CALR (calreticulin)
Diseases named in the same sentence as CALR in open-access papers (continued):
Sharing a sentence is not in itself a finding about the gene and the disease.
tumor (continued). "This was demonstrated by showing that in vitro treatment with opaganib increases the surface expression of the ICD marker calreticulin on a variety of tumor cell types." (PMID 38069222, 2023). "Surface exposure of calreticulin by tumor cells in treated tumors speaks in favor of such phenomena." (PMID 37782273, 2023). "CALR exposed on the surface of tumor cells can trigger phagocytosis and initiate the anticancer immune response." (PMID 37947594, 2023). "CM was enriched with proteins such as calreticulin, which acted as an extracellular tumor suppressor by interacting with CD47." (PMID 36943734, 2023). "Irradiation is known to induce immunogenic cell death characterized by releasing of tumor antigens and damage-associated molecular patterns (DAMPs) such as HSP70, HMGB1, and calreticulin." (PMID 36545361, 2023). "The process of calreticulin translocation to the surface of tumor cells treated with certain therapeutic factors involves the secretion of ATP, Hsp70/90 and HMGB1 into the medium." (PMID 37880798, 2023). "Today it is known that calreticulin secreted by T. cruzi plays a protective role in cancer by increasing tumour immunogenicity and inhibiting tumour growth." (PMID 37424156, 2023). "In the tumor acidic environment, TTA-Q6 is released, disrupting cancer cell calcium uptake, causing endoplasmic reticulum stress and inducing calreticulin transfer to the cell surface." (PMID 37951973, 2023). "Further investigation revealed a significant correlation between CALR and tumor-infiltrating immune cells." (PMID 36907982, 2023). "The tumor’s secreted STC1 has been identified to interact with calreticulin (CRT), an “eat-me” signal, leading to reduced CRT membrane exposure." (PMID 38159261, 2023). "Further studies demonstrated that ICD tumor cells expressed a lot of DAMPs, some of which expose on the cell membrane, including CALR, HSP70 and HSP90, to act as “eat me” signals for APCs." (PMID 37684628, 2023). "Compared with the control group, free Dox elicited an increasing release of intratumoral, high-mobility group box-1 (HMGB1), as well as overexpression and exposure of calreticulin (CRT) on the surface of tumor cells." (PMID 37620331, 2023). "Calreticulin exposure is an important marker of ICD of tumor cells, providing immune cells with an “eat me” immunogenic signal." (PMID 38132921, 2023). "It plays an essential role in the tumor immune evasion and immunotherapy resistance by trapping calreticulin in mitochondria and the ER to inhibit macrophage function." (PMID 36882399, 2023). "Studies in the cancer field have shown the translocation of intracellular CALR to the cell surface is required for phagocytosis of apoptotic tumor cells by dendritic cells and induction of an effective immune response, including priming of cytotoxic T cells." (PMID 37692787, 2023). "The value IC50 for CW-MSC CM was 390 μg/ml, while IC50 for the selected tumor-suppressing proteins ranged from 1.1 μg/ml (CALR) to 5.8 μg/ml (HSP)." (PMID 36943734, 2023). "Tumor-specific T cells are drawn to tumors by the biomarkers associated with ICD, such as calreticulin, high-mobility group box 1, and ATP33." (PMID 37932362, 2023). "Herein, we demonstrate that an opaganib concentration that can be achieved in vivo promotes calreticulin surface expression of a variety of tumor cell types." (PMID 38069222, 2023). "Consistently, immunohistochemical analysis showed a decrease in Ki-67 and an increase in cleaved caspase 3 in tumor-invaded bone sections by the administration of CALR." (PMID 36943734, 2023). "During the initiation stage of MMC-induced immunogenic cell death of tumor cells, chaperone calreticulin translocates to the surface of membrane, which represents an immunogenic “eat-me” signal for DCs in phagocytosis." (PMID 37631898, 2023). "Human tumor tissues exhibit significantly higher levels of Calreticulin (HuCalr) compared to normal tissues." (PMID 38188016, 2023).
tumor (continued). "Raji tumor cells express pro-phagocytic molecules such as calreticulin together with CD47, and the interaction of hCD47 on Raji cells with hSIRPα on human macrophages likely inhibits phagocytosis of tumor cells." (PMID 38162643, 2023). "Treatment of tumor cells with anthracycline-induced calreticulin (CRT) membrane translocation is essential for tumor cell phagocytosis by dendritic cells and the antitumor immune response." (PMID 37781042, 2023). "When ICD occurs in tumor cells, dead tumor cells calreticulin (CRT) will be exposed to the cell surface." (PMID 36976060, 2023). "Chemotherapeutic drugs such as taxanes (docetaxel and paclitaxel) and vinca alkaloids (vinorelbine and vinblastine) can enhance tumor cell recognition by increasing calreticulin exposure and killing tumor cells." (PMID 36979400, 2023). "Specifically, we conducted an immunohistochemical (IHC) experiment to validate the expression levels of Calreticulin (CALR) in both tumor and adjacent tissues, and evaluated its prognostic significance using the Kaplan-Meier (KM) curve." (PMID 38023241, 2023). "Flow cytometric analysis indicated that SNPA CALR&aCD47 increased the percentage of tumor cell‐ingested macrophages by more than twofold compared with CALR+aCD47+ SNPA or SNPA CALR + SNPAaCD47." (PMID 36794651, 2023). "We have shown previously that a tumor-suppressing protein, CALR, inhibited the progression of osteosarcoma cells via interaction with CD47." (PMID 37056934, 2023). "Studies conducted previously have discovered that individuals with BLCA exhibit a greater expression of CALR in both tumor tissues and urine compared to healthy individuals." (PMID 38023241, 2023). "Among the candidates for the role of Hsp70 binders, we also considered the high mobility group B1 protein, HMGB1 and calreticulin, both known DAMPs and markers of tumor relapse after radiotherapy." (PMID 37880798, 2023). "Dendritic cells are recruited to dying tumor cells by ATP, engulfing tumor antigens when stimulated by calreticulin and presenting tumor cell antigens to T cells when stimulated by HMGB-1." (PMID 36982933, 2023). "Alternatively, the selection of potent tumor-suppressing proteins such as CALR, ENO1, PCOLCE, etc. can be another option to construct a protein cocktail." (PMID 36943734, 2023). "Tetraploid tumor cells exhibit increased exposure of the calcium chaperone calreticulin (CALR) to the plasma membrane, where it acts as an “eat me” signal to the immune system." (PMID 37047342, 2023). "To expand these studies, we measured the effects of in vitro opaganib treatment on the expression of calreticulin in a panel of diverse tumor cell lines." (PMID 38069222, 2023). "Mechanistically, Casp8 deficiency or pharmacological disruption results in impaired ecto-calreticulin transition in tumor cells, which in turn hampers antigen presentation in draining lymph nodes." (PMID 36635765, 2023). "As for the anti-tumor regulatory mechanism, we focused on CALR and procollagen C-endopeptidase enhancer (PCOLCE)." (PMID 36943734, 2023). "CALR is expressed on the tumor cell membrane and promotes phagocytosis of macrophages by interacting with low density lipoprotein receptor‐associated protein 1 on macrophages." (PMID 36794651, 2023). "In the TCGA database, five transcripts for the selected tumor-suppressing proteins (CALR, ENO1, HSP, MSN, and UBC) were significantly upregulated in OS cells." (PMID 36943734, 2023). "Anthracyclines and oxaliplatin stimulate calreticulin to transfer from the intracellular site to the outer surface of the cell membrane where it is recognized by DCs and presented as tumor antigens, thus initiating the ICD process." (PMID 37600822, 2023). "Membrane exposure of calreticulin acts as a phagocytic signal and attracts antigen presenting cells to the tumour site and promotes their subsequent activation and maturation." (PMID 35986757, 2023).
tumor (continued). "Among extracellular tumor-suppressing proteins, some proteins (e.g., HSP90β) are considered secretory proteins, while others (e.g., CALR) are cell-surface proteins." (PMID 37056934, 2023). "Tumor cells have been reported to overexpress certain endoplasmic reticulum stress proteins including calreticulin (CRT) on their cell surface." (PMID 37345057, 2023). "Previous studies for iTSCs showed that MSC CM, generated by the activation of Wnt and PI3K signaling pathways, were enriched with extracellular tumor-suppressing proteins such as CALR, ENO1, HSP, MSN, and UBC." (PMID 36943734, 2023). "This nanosystem comprises epirubicin (EPI), glucose oxidase (Gox), and hemin encapsulated in a MOF-based NP and is further coated with the calreticulin-overexpressed tumor cell membrane." (PMID 37376125, 2023). "ATP releases dendritic cells to the site of the tumor, and cells such as calreticulin contribute to the uptake of tumor antigens by these cells." (PMID 37762219, 2023). "Another tumor promoter that was downregulated after treatment with Z-guggulsterone was calreticulin." (PMID 36014345, 2022). "The cytotoxic agent doxorubicin further induced calreticulin expression on the tumor cell surface and promoted macrophage-dependent phagocytosis in vitro." (PMID 35565307, 2022). "The overexpression of CALR in a tumor cell line effectively increased the Ca2+ buffering capacity and protected cells against apoptosis." (PMID 35769266, 2022). "To access the mechanism of anti-tumor, anti-inflammatory actions of YS MSC CM, we selected five tumor suppressors (Hsp90ab1, calreticulin, histone H4, polyubiquitin C, and enolase 1) based on our previous whole-genome proteomics analysis." (PMID 35804814, 2022). "ICD is mainly characterized by calreticulin (CRT) exposure at the cell surface of dying tumor cells, the release of the ATP, HMGB1 (High-Mobility Group Box 1) and annexin A1 (ANXA1) in the extracellular space." (PMID 36429101, 2022). "They observed that this strategy increased the expression of calreticulin in target tumor cells, reducing tumor growth due to immune activation." (PMID 36015189, 2022). "Injection of recombinant calreticulin or blockade of eIF2α dephosphorylation increased immunogenicity of tumor cells and had a therapeutic benefit in tumor-bearing mice." (PMID 35806328, 2022). "Calreticulin is a potential biomarker and therapeutic target for various cancers, including HCC, and its overexpression is linked with the acceleration of tumor cell migration and invasion." (PMID 36014345, 2022). "In terms of microevolution, it makes sense, as calreticulin is a molecule that activates tumor cell phagocytosis by APC." (PMID 36015189, 2022). "In recent studies, CALR has attracted extensive attention owing to its influence on tumor progression, malignant transformation, and response to therapy." (PMID 36338983, 2022). "This biomarker’s function is to target proteins, Calreticulin and Mucin-1, which have roles in calcium storage, gene expression regulation, genotoxic stress regulation and tumor suppression." (PMID 35453967, 2022). "At the cellular level, RT induces tumour cells to express calreticulin—an ‘eat me signal’—that binds CD91 (α2‐macroglobulin receptor) on APCs, enhancing tumour cell endocytosis for antigen presentation." (PMID 35261190, 2022). "RT induces the immunogenic death of cancer cells, which is characterized by the transfer of calreticulin to the surface of dying tumor cells together with high-mobility group box-1 and adenosine triphosphate release." (PMID 35656295, 2022). "According to current research, several chemotherapy drugs, such as taxanes and vinca alkaloids, can make it easier to identify tumor cells by increasing calreticulin exposure and destroying tumor cells by creating a lot of tumor antigens." (PMID 36419058, 2022).
tumor (continued). "Although cytotoxic CD8 T cells are often the primary mediators of anti-tumor specific cytolysis, we have previously shown low CALR-specific CD8 T cell-responses in MPN." (PMID 35603202, 2022). "CXCL12 addition to tumor cells also induces the release of damage associated molecular patterns such as ATP, HMGB1 and calreticulin; in turn, HMGB1 can promote the secretion of CXCL12." (PMID 35565443, 2022). "The rationale for this strategy is supported by the fact that some tumor types have a reduced expression of DAMPs, such as calreticulin." (PMID 36015189, 2022). "The encased doxorubicin can induce the immunogenic death of cancer cells and upregulate the expression of CD47 and calreticulin on the surface of cancer cells, while R837 can activate dendritic cells for enhanced processing and presentation of tumor antigens." (PMID 36341415, 2022). "After chemotherapy, the cell membrane surfaces of dying tumor cells expose calreticulin (CALR) and heat shock proteins (HSPs) and then release DAMPs." (PMID 36579538, 2022). "Compared with the matched normal tissues, the highly expressed CALR was detected in different types of tumors (TCGA tumor vs TCGA normal), including LUAD and LUSC." (PMID 35264066, 2022). "Phylogenetically conserved chemokine signaling via CXCL8 increases the exposure of calreticulin on the tumor cell surface, which is critical for dendritic cells (DCs) to recognize and engulf dying tumor cells." (PMID 35656295, 2022). "We then compared the CALR expression level across different tumor cell-lines between pre- and post-ICB treatment and responders and non-responders." (PMID 35418980, 2022). "The expression of CALR mRNA in pan-cancer and immune infiltrates was analyzed using the Tumor Immune Estimation Resource (TIMER) database." (PMID 36338983, 2022). "UTMD can increase antigen release, heat shock protein expression, calreticulin levels and pro-phagocytic signals, affecting the tumor microenvironment and comprehensively stimulating tumor immunity." (PMID 35844515, 2022). "This indicates that tumor cells can avoid the effect of CALR through CD47, so as to prevent immune killing caused by physiologically dead tumor cells via CALR in the process of tumorigenesis." (PMID 36293504, 2022). "Third, the release of DAMPs including ATP, HMGB1, HSP70, and calreticulin from tumor cells are vital for inducing ICD." (PMID 35740542, 2022). "Delta-24-ACT infection triggered the translocation of calreticulin to the plasma membrane, another well-known mechanism that contributes to the immunogenicity of tumor cells by acting as an “eat-me” signal to promote tumor cell phagocytosis by macrophages." (PMID 35393952, 2022). "Of the markers of immunogenic cell death described in the Consensus guideline in 2015, only HMGB1 can be measured in blood serum and plasma, as adenosine triphosphate (ATP) acts in the tumor microenvironment and calreticulin is exposed on tumor cells." (PMID 34671818, 2022). "“Eat me” and “danger” signals such as calreticulin (CRT) become expressed on the surface of tumor cells undergoing ICD." (PMID 36361831, 2022). "The calreticulin (CRT), a soluble ER-associated chaperone, is one of the ferroptosis-mediated proteins which regulate the tumor microenvironment." (PMID 35832539, 2022). "NcRNA-RB1 (a lncRNA expressed in the RB1 promoter) suppresses the expression of calreticulin, which is a calcium-binding chaperone and affects the presentation of antigen to cytotoxic T cells, and prevents tumor cells release “killing me” signal." (PMID 35606755, 2022). "Cells undergoing ICD release and express damage-associated molecular patterns (DAMPs), e.g., calreticulin, heat-shock protein 70 and 90, ATP, and/or HMGB1, which attract antigen-presenting cells (APCs) to the tumor side." (PMID 35892641, 2022).
tumor (continued). "Instead, the anti-GD2 antibody disrupted the binding of GD2 to a newly identified ligand associated with inhibitory signaling on macrophages, Siglec-7, while upregulating calreticulin on the surface of the tumor cells." (PMID 35565307, 2022). "If dying tumor cells exhibit CALR, which binds to SR-A, LRP1, and SREC-1 on DCs, they will be phagocytosed quickly." (PMID 35488303, 2022). "When exposed on the plasma membrane of cancerous cell undergoing ICD, calreticulin enhances phagocytosis by dendritic cells, a crucial step for tumor antigen presentation." (PMID 35903697, 2022). "Mechanistic studies reveal that anti‐PD‐L1‐DOX‐R848‐MIP‐3α/TKNP specifically targets tumor tissue, resulting in maximum exposure of calreticulin (CRT) and HMGB1 in tumors, and significantly enhances intratumoral infiltration of CD4+ and CD8+ T cells in tumors." (PMID 37693071, 2022). "ICD inducer-treated tumor cells stimulate the exposure of tumor-associated antigens, known as damage-associated molecular patterns (DAMP), including calreticulin." (PMID 36419893, 2022). "Direct treatment of tumor cells with CAP can alsotrigger ICD by inducing the exposure of calreticulin and HSP70 on the outermembrane, as well as secretion of ATP and HMGB1." (PMID 35441043, 2022). "Dying tumor cells expose the CALR/ERp57 complex to the cell surface, triggering a powerful anticancer immune response." (PMID 36579538, 2022). "In order to study the molecular mechanism of CALR involved in tumor progression, we used String and GeneMANIA databases finding that PDIA3, B2M, GANAB, CANX, and TAPBP interact with CALR." (PMID 34910788, 2021). "The expressionof calreticulin, a marker of immune response activation, was measuredin tumor cells after in vivo application of MH treatment,paying special attention to differences between cells that had orhad not internalized particles." (PMID 33709682, 2021). "Tumor masses explanted from mice treated with BoxA displayed calreticulin on the surface of cells, contrary to tumors from untreated mice." (PMID 33956406, 2021). "ANXA1 binds formyl peptide receptor 1 (FPR1) thus facilitating DC homing to dying cells in the tumor bed, and CALR stimulates tumor antigen engulfment by DCs." (PMID 33809187, 2021). "A recent study demonstrated that macrophage-mediated anti-tumor immunity was found to be enhanced upon intratumoral injection of nanoparticles containing calreticulin." (PMID 33790906, 2021). "Membranous CALR exposure act as strong “eat me signals” so that dendritic cells and macrophages possessing the CD91 receptor become engaged as participants in the cancer-immunity cycle through active phagocytosis of CALR expressing tumor cells." (PMID 34869014, 2021). "For example, CALR promotes the uptake of tumor cells by enhancing phagocytosis in macrophages, and the mutation of CALR alters the proliferation of hematopoietic cells." (PMID 34638846, 2021). "By activating dendritic cells (DC) and cytotoxic T cells, CALR leads to tumor cell ICD as phagocytic signals." (PMID 34910788, 2021). "It has been reported that CALR expression in tumor cells correlates with eIF2α phosphorylation and DC infiltration, which positively influences the clinical outcome of NSCLC." (PMID 34660305, 2021). "Calreticulin is essential for the recognition of tumor cells by DCs and subsequently by T cells, in fact, depletion of calreticulin in the tumor cells reduced the T cell killing." (PMID 34768644, 2021). "Radium-223 enhanced T cell-mediated lysis of tumor cells through upregulation of major histocompatibility complex class I molecules and increased cell surface expression of calreticulin on tumor cells." (PMID 34084750, 2021).